MIR3157 (microRNA 3157)
Synonyms: hsa-mir-3157; mir-3157
Gene: MicroRNA gene on chromosome 10 (96,064,315 to 96,064,399, reverse strand). Ensembl gene ENSG00000266407.
Homologues: Orthologues: chimpanzee MIR3157 (100% identical).